OPRPN (opiorphin prepropeptide)
Description:
Opiorphin is an endogenous inhibitor of neprilysin and aminopeptidase N. Inhibits the breakdown of substance P, Mca-BK2 and Met-enkephalin by neprilysin in vitro with IC(50) values of 29 uM, 33 uM and 33 uM respectively. Inhibits the breakdown of Ala-pNA by aminopeptidase N in vitro with an IC(50) of 65 uM. Has a potent analgesic effect when administered to rats by intravenous injection.
Synonyms: PRL1; BPLP; PROL1; opiorphin
Tractability: Antibody: UniProt places it where antibodies can reach, with high confidence; its Gene Ontology location is reachable by antibodies, with high confidence; UniProt predicts a signal peptide or a membrane-spanning region.
Gene: Protein-coding gene on chromosome 4 (70,397,931 to 70,410,195, forward strand). Ensembl gene ENSG00000171199.
Subcellular location: Secreted
Gene Ontology:
Molecular function: endopeptidase inhibitor activity; peptidase inhibitor activity
Biological process: regulation of sensory perception of pain
Cellular component: extracellular region
Genetic constraint (gnomAD): Loss-of-function variants: 0 observed, 1.23 expected, observed/expected ratio (o/e) 0, 90% interval 0 to 1.65. That is too few expected variants to judge how well the gene tolerates losing a copy. Missense variants: 290 observed, 294.22 expected, observed/expected ratio (o/e) 0.99, 90% interval 0.89 to 1.09. Synonymous variants: 119 observed, 109.78 expected, observed/expected ratio (o/e) 1.08, 90% interval 0.93 to 1.26.
Homologues: Orthologues: chimpanzee OPRPN (96% identical), macaque OPRPN (87% identical).
Diseases named in the same sentence as OPRPN in open-access papers:
OPRPN is named in the same sentence as 10 diseases in open-access papers, as found by Europe PMC text mining. Sharing a sentence is not in itself a finding about the gene and the disease. The quoted sentences say what the papers report.
Myalgia (1 paper, 2025). "For the rs1387964 polymorphism in the OPRPN gene (recessive model), the frequency of individuals with the homozygous CC genotype was significantly higher in both arthralgia (12.2%) and myalgia (14.5%) groups compared to controls (3.5% in both comparisons)." (PMID 40868215, 2025). "TMDp myalgia showed significant associations with the OPRPN rs1387964 variant, female sex, age, and psychological characteristics, highlighting the multifactorial nature of this subtype." (PMID 40868215, 2025). "The rs1387964 polymorphism in the OPRPN gene was a strong and significant predictor of myalgia in both models." (PMID 40868215, 2025). "This association was observed in the OPRPN gene, where the minor allele homozygous (CC genotype) was more prevalent in both the arthralgia (p = 0.040) and myalgia (p = 0.025) groups compared to healthy controls." (PMID 40868215, 2025).
OPRPN also shares sentences with these, for which no sentence is quoted: metastatic disease (2 papers); cancer (1); infection (1); ischemia (1); melanoma (1); metastatic melanoma (1); prostate carcinoma (1); skin cancer (1); tumor (1).